BRCA1 (BRCA1 DNA repair associated)
Diseases named in the same sentence as BRCA1 in open-access papers (continued):
Sharing a sentence is not in itself a finding about the gene and the disease.
cancer (continued). "If a genetic test reveals a germline pathogenic variant in a cancer predisposition gene such as BRCA1 or BRCA2, family members also become eligible for a genetic test." (PMID 34617209, 2022). "One article from India suggested that the mutual interaction between Centrosomal Protein 112 (CEP112) and breast cancer type 1 susceptibility protein (Brca1) was significant in the mitotic regulation and maintenance of genomic stability." (PMID 36552760, 2022). "Four PARP inhibitors have been approved for the treatment of BRCA1- or BRCA2-deficient cancers, leading to promising clinical responses." (PMID 35349716, 2022). "A high BRCA1/2 mutation rate of 38.9% has also been demonstrated in Taiwan in a cohort of 18 synchronous/metachronous BROV cancer studies." (PMID 35608067, 2022). "The clinical efficacy was evident in other cancer types due to BRCA1/2 or other deleterious mutations in the HR pathway (such as ATM), specifically pancreatic and prostate cancers." (PMID 36358724, 2022). "Regarding age, research underlined that older age is associated with assisted reproductive technology use; in fact, in men and women with BRCA1/2 pathogenetic variant, the older the age, the greater the risk of developing cancer." (PMID 35661074, 2022). "BRCAness defines the pathogenesis and treatment sensitivity of many types of cancer, as well as the presence of a defect in the homologous recombination repair of tumor cells simulating the loss of BRCA1 or BRCA2, as in the presence of germline mutations." (PMID 36613648, 2022). "This synthetic lethal interaction between PARP blockade and BRCA1/2 mutation suggests a therapeutic strategy targeting PARP for treatment of cancer types harboring BRCA mutations." (PMID 36224343, 2022). "This one result is due to a mutation in the DNA repair gene BRCA1 (Breast cancer gene 1) or BRCA2 (BRCA1); a loss of function of this gene induces an alteration of DNA repair and hence the development of cancer." (PMID 35327559, 2022). "Taking the advantage of longer cancer-free time, early cancer prevention for the mutation carriers can be achieved if the BRCA1 mutation-caused transformation process can be blocked before cancer development." (PMID 35869059, 2022). "Regarding DNA repair, cancers with mutations in BRCA1/2 (Breast Cancer Associated Genes 1 and 2) can be treated with PARP (Poly-ADP-Ribose-Polymerase) inhibitors originally established in Ovarian Cancer." (PMID 35222436, 2022). "We considered that Brca1-mutated mouse model will be ideal for the study as mouse model has been widely used to study the relationship between Brca1 mutation and cancer." (PMID 35869059, 2022). "For each patient, we also showed the risk in the well-known high-penetrance cancer risk alleles BRCA1 and BRCA2 with respect to other moderate-penetrance alleles including PALB2, CHEK2, ATM, BARD1, RAD51D, RAD51C and BRIP1." (PMID 35886069, 2022). "Cancer genomes of patients with BRCA1/2 mutations are enriched with particular mutational patterns as well as a high number of distinct LOH regions." (PMID 35783256, 2022). "Participants’ age, presence of offspring, and their family history of BRCA1/2 mutation related-cancer risk were all entered as control variables, and multi-item constructs were estimated as latent factors." (PMID 35303741, 2022). "For example, PARP3, 9 are overexpressed in different types of human cancers, including BRCA1-associated cancers and DLBCL." (PMID 35652091, 2022). "PARPis are potentially synthetic lethal effects for the treatment of cancers characterized by specific DNA-repair defects, such as tumor cells that contain BRCA1 and/or BRCA2 (BRCA1/2) mutations and present defects in homologous recombination repair." (PMID 36034834, 2022). "The FDA has approved a number of mutations for cancer screening or cancer assaying, including mutations in the BRCA1 and BRCA2 genes for ovarian cancer, ALK rearrangements for NSCLC, and alterations in the PIK3CA gene for breast cancer patients." (PMID 35053452, 2022).
cancer (continued). "The BRCA1insC mutation is one of the relatively common Ashkenazi Jewish BRCA1 founder mutations that are known to increase the risk for cancer." (PMID 36346676, 2022). "This establishes a rationale for the therapeutic application of PARPi-induced synthetic lethality in BRCA1/2-mutated/deficient cancer cells." (PMID 36497275, 2022). "Although additional research is necessary to confirm certain associations, sufficient information is available to use certain risk factors in risk counseling or lifestyle modification to reduce cancer risk in BRCA1/2 mutation carriers." (PMID 35885460, 2022). "BRCA1/2 pathogenic variants increase the risk of multiple cancers including breast, ovarian, prostate, pancreatic, and uterine cancers which are identified as BRCA-associated cancers." (PMID 35578198, 2022). "Our data demonstrated that the constitutive exposure of PS on the cell membrane caused by ATP11Blo and PTDSS2hi in Brca1-MT cancer is critical for triggering cancer metastasis." (PMID 35025764, 2022). "Classically, BRCA1/2 mutated cancer is supposed to respond to PARPis via synthetic lethality; that is, PARPis inhibit BER so that SSB converts into DSB subsequently." (PMID 35281059, 2022). "We next evaluated the changes occurring at the level of ubiquitination between the cancer tissues with different BRCA1 mutational status." (PMID 35292711, 2022). "In our real-world Cohort III, BRCA1/2 biallelic pathogenic alterations occurred in 73.4% (58/79) of all BRCA1/2-mutant cases which were all identified in BRCA-associated cancers." (PMID 35578198, 2022). "BRCA1/2 are tumor suppressor genes that are clinically linked to a hereditary predisposition to developing cancer." (PMID 35158750, 2022). "As a typical tumor suppressor gene, the inactivation of the second wild-type (WT) BRCA1 allele is expected to trigger cancer initiation." (PMID 35039532, 2022). "The best-known genetic mutations associated with this cancer include mutations in the BRCA1 and BRCA2 genes." (PMID 35626173, 2022). "PARPi are specifically lethal to cancer cells that cannot repair DNA damage by homologous recombination (HR), and HR deficiency is frequently associated with BRCA1/2 mutations." (PMID 35203410, 2022). "Self-efficacy, outcome expectancies, risk perception and family history of BRCA1/2-related cancers play a defining role in men’s decisional process leading to genetic screening." (PMID 35303741, 2022). "Inhibition of poly-(ADP-ribose) polymerase (PARP), a key enzyme in base excision repair, efficiently kills cancer cells with defective Homologous recombination (HR) in BRCA1/2 deficient cancer, which turned as synthetic lethal due to enhanced DNA damage." (PMID 35346236, 2022). "Research on PARP inhibitors beyond BRCA1/2-mutated carcinomas, for example, is pioneering the field of personalized medicine." (PMID 35805063, 2022). "Secondary somatic mutations that restore BRCA1/2 in carcinomas from women with germline BRCA1/2 mutations predict the resistance to platinum and PARPIs." (PMID 35785170, 2022). "GSEA with our LATS-null ranklist displayed a strong enrichment for upregulated genes in the Brca1f/f; p53f/+; Blg-Cre model, suggesting a correlation between LATS1/2 inactivation and basal-like carcinomas driven by the Brca1 mutation." (PMID 36443313, 2022). "While great strides have been made in identifying synthetic lethal interactors of BRCA1, cancer metastasis remains the leading cause of death for all cancers." (PMID 35008272, 2021). "The location of the mutation strongly determines cancer risk and the response of the respective BRCA1-mutant tumor or cell line to chemotherapeutics, including PARP inhibitors (PARPi) and cisplatin." (PMID 35008272, 2021). "This study aimed to elucidate the cancer spectrum, family history of cancer, and outcomes of male patients with BRCA1/2-mutations." (PMID 34575694, 2021).
cancer (continued). "Patients who carry a germline pathogenic mutation in the BRCA1/2 gene have a significantly increased risk of developing BC and other cancers (e.g., ovarian, pancreatic, and prostate cancer)." (PMID 34354733, 2021). "As BRCA1 functions as a tumor suppressor, we only selected the cancer samples with loss-of-function mutations of BRCA1, including deep deletion, truncating mutation and missense mutation (putative driver) as BRCA1-deficient cancers for further analysis." (PMID 34815798, 2021). "Using the genetic concept of synthetic lethality, PARP inhibitors are designed to target cancers harbouring specific DNA-repair defects, including those arising in carriers of BRCA1 or BRCA2 mutations." (PMID 33705352, 2021). "The prevalence of CNVs in established BC/OC predisposition genes is poorly studied, and current data are either limited to BRCA1/2 only or based on small study samples for some non-BRCA1/2 cancer predisposition genes." (PMID 33401422, 2021). "Evidence is less clear regarding men with cancer-predisposing BRCA1 variants but they probably also have an increased risk." (PMID 34649841, 2021). "PARP inhibition in BRCA1‐deficient cancers has been reported to cause apoptosis as well as senescence." (PMID 33660437, 2021). "Our findings are similar to two other studies investigating the cancer spectrum of male BRCA1/2-mutation carriers, where a higher number of overall cancers as well as BC were observed in patients with a BRCA2-mutation." (PMID 34575694, 2021). "Healthy individuals and patients with cancer who are carriers of germline pathogenic variants in the BRCA1/2 genes face multiple reproductive challenges that require appropriate counseling and specific expertise." (PMID 34503502, 2021). "Germline mutations in BRCA1 or BRCA2 tumour suppressor genes predispose to different cancers, as does oncogene activation." (PMID 34389725, 2021). "Patients harboring BRCA1/2 mutations in tumor specimens should therefore be referred to genetic counselling to identify a familial cancer predisposition." (PMID 34202525, 2021). "But the most remarkable pro-cancer RAD52 phenotype is seen in cancer cells deficient in any of the following DNA repair proteins: BRCA1, BRCA2, PALB2, XAB2 or RAD51 paralogs: RAD51B, RAD51C, RAD51D, XRCC2 and XRCC3." (PMID 34887904, 2021). "A single unrepaired DSB in a cell can be cytotoxic, additionally mutations or down-regulation of DNA repair proteins, associated with the repair of DSBs, are strongly linked with inherited cancer risk (BRCA1, BRCA2, ATM)." (PMID 33669398, 2021). "In the case of BRCA1/2 mutation carriers, the representation of the health threat (cancer) is mostly formed through direct experiences with family members, but is also influenced by friends, media and cultural beliefs." (PMID 34069035, 2021). "The paradigm for this approach is the use of poly(ADP)-ribose polymerase inhibitors (PARPi) for the treatment of homologous recombination-deficient (HRD) cancers, which includes breast and ovarian tumors that are mutated in the HR genes BRCA1 and BRCA2." (PMID 33333017, 2021). "New cancer-predisposing gene (CPG) candidates have been investigated with a focus on members of the Fanconi anaemia (FA) DNA repair pathway involving BRCA1 and BRCA2 function." (PMID 34861889, 2021). "These cells also had increased DNA damage following treatment with drugs that block PARPs, similar to cancer cells carrying mutations in the gene for BRCA1." (PMID 34142659, 2021). "The genes that regulate development are frequently associated with cancers and variations in genes critical functions, such as DNA damage and repair, including BRCA1, increase susceptibility to NSCLP." (PMID 34941638, 2021). "Although PARPi are effective in many BRCA1/2 and HR deficient cancers, resistance often develops for a number of reasons." (PMID 33498235, 2021).
cancer (continued). "In total, 29 germline pathogenic/likely pathogenic variants were identified in autosomal dominant cancer predisposition genes where the gene was pertinent to the cancer family history (including BRCA1/BRCA2, the mismatch-repair genes and APC)." (PMID 33654310, 2021). "Unfortunately, it is well established that BRCA1-mutated cancers can develop cisplatin resistance through a secondary mutation that restores BRCA1 function." (PMID 34360968, 2021). "So far, known genetic determinants of HPC are deleterious mutations in pan-cancer DNA repair genes (e.g., BRCA1, BRCA2, ATM, etc.)or in the PCa-specific risk genes, HOXB13." (PMID 33947030, 2021). "The frequency of pathogenic variant carriers among these cancer patients were 6.3%, with BRCA1/2 carriers accounted for 5.1%." (PMID 35070997, 2021). "For OC patients with BRCA1/2 cancer driver mutations, PARP inhibitors are the standard of care rather than immunotherapy." (PMID 34503126, 2021). "Meanwhile, both germline and somatic BRCA1 mutations were strongly correlated with basal cancer subtype." (PMID 33525353, 2021). "PARP inhibitors have been developed to treat multiple cancer types with BRCA1/2 mutations, thereby creating synthetic lethality in BRCA1/2-defective cells." (PMID 34948368, 2021). "We uncover DDX11 as a potential target in tumors, including BRCA1/2-mutated cancers that acquired chemotherapeutic resistance, and pinpoint DDX11 mutations/loss as a useful biomarker of responsiveness to platinum drugs, PARP inhibitors, and ATRi." (PMID 33879618, 2021). "For example, somatic BRCA1/2 reversion mutations are often identified in patients with BRCA1/2-mutated cancers after treatment with platinum-based therapy, causing restoration of HR capacity and thus conferring PARPi resistance." (PMID 33487630, 2021). "We demonstrate that oncogenic β-catenin activation acts synergistically with BRCA1/2 deficiency in eliminating cancer cells and we identify the underlying mechanism as transcriptional deregulation of specific gene targets, with genotoxic consequences." (PMID 34389725, 2021). "Since the median age at cancer diagnosis in SMARCA4 mutation carriers is lower as compared to BRCA1/BRCA2 mutation carriers, the prophylactic surgery should be offered at least earlier, preferably below the age of 22." (PMID 33907931, 2021). "All BC patients will benefit from genetic counseling at the POC, as BRCA1/2 variant carriers with a high-risk MammaPrint 70-gene profile are at increased risk for both local and distant/metastatic recurrence of their cancer." (PMID 34660253, 2021). "Inhibition of PARP activity was shown to be highly cytotoxic to cancer cells with dysfunctional HR due to BRCA1/2 deficiencies." (PMID 34363951, 2021). "The availability of affordable benchtop NGS systems offered the possibility to transfer the BRCA1/2 diagnostic workflow onto these high-throughput platforms, to improve and optimize the molecular diagnosis of mutational events in cancer." (PMID 34068254, 2021). "Individuals with identified pathogenic variants in the BRCA1/BRCA2 gene can benefit from cancer risk-reducing strategies." (PMID 34525964, 2021). "To model the BRCA1-deleted stroma, we first generated induced pluripotent stem cells (iPSCs) from patients carrying a germline deletion of exon 17 of the BRCA1 gene (BRCA1+/− who, based on their family histories, were at a high risk for cancer." (PMID 33513753, 2021). "Our data thus far indicated that GSK3 inhibition strongly synergized with PARPi in BRCA2-deficient and BRCA1/2-proficient cancer cells in vitro." (PMID 33589588, 2021). "Within 63 BRCA1-deficient cancers, related RNA-seq data were available from 13 samples in TCGA database." (PMID 34815798, 2021). "Gene and protein expression profiling has revealed that cancers arising as a result of a BRCA1 deficiency show triple-negative and basal-like properties, tend to be aggressive, and typically have a poor prognosis 6,7." (PMID 33767581, 2021).
cancer (continued). "The prevalence assessment of novel and recurrent BRCA1/2 pathogenic mutations will enhance the use of personalized treatment and precise screening strategies by both affected and unaffected North African cancer cases." (PMID 34490083, 2021). "Several reports have also demonstrated that patients with cancer frequently carrying BRCA1 mutation are susceptible to CDDP treatment." (PMID 33397362, 2021). "Multiple essential HR genes, including breast cancer susceptibility gene 1/2 (BRCA1/2) and recombinase Rad51, are recruited to damaged DNA to facilitate repair." (PMID 34880209, 2021). "We were curious to see if RPA:RAD52 PPI inhibitors would show synthetic lethality in HR-deficient cancer cell lines, so we examined the cytotoxicity of quinacrine, mitoxantrone, and doxorubicin in cells with impaired BRCA1 or BRCA2 function." (PMID 33784323, 2021). "In the majority of cases, the BRCA1 or BRCA2 PVs are inherited from one of the parents accompanied by a cancer susceptibility transmitted as an autosomal dominant trait." (PMID 34026625, 2021). "The proteins encoded by the breast cancer gene 1/2 (BRCA1/2) genes participate in the repair of DNA double strand breaks." (PMID 34253236, 2021). "In studies of mothers undergoing BRCA1/2 testing, stronger tendencies to worry/ruminate about cancer risk information, greater psychological strain, and poorer coping skills are identified as barriers to open family communication." (PMID 34565430, 2021). "The global association of BRCA1/2 mutations with diverse forms of cancer is likely due to the crucial function of both BRCA1 and BRCA2 in DNA repair systems, which are cornerstone to physiological functionality and maintenance of cells throughout the body." (PMID 34070674, 2021). "Since BRCA1/2 gene mutations occur at a relatively high frequency in BC, to predispose an individual with developing BC and other cancers, PARP inhibitors are regarded as one of the potential targeted drugs for gBRCA mutant BC." (PMID 34354733, 2021). "First-line maintenance treatment with PARPi is available through the Cancer Drugs Fund for people with a BRCA1 or BRCA2 gene mutation." (PMID 33808557, 2021). "Inhibitors of PARPs, approved for cancer chemotherapy a few years ago, have achieved great success against tumors of the breast and ovary carrying mutations in the BRCA1/2 genes." (PMID 33922595, 2021). "Overall, these data confirm that in addition to sensitizing cells to PARG inhibition, loss of ARH3 confers PARPi resistance in different types of cells, including BRCA1/2-deficient cancers." (PMID 34019811, 2021). "The tumor suppressor protein partner and localizer of BRCA2 (PALB2) orchestrates the interactions between breast cancer susceptibility proteins 1 and 2 (BRCA1, -2) that are critical for genome stability, homologous recombination (HR) and DNA repair." (PMID 34946951, 2021). "Advances have also been made in the application of PARPi in cancers other than HBOC with BRCA1/2 germline or somatic mutations." (PMID 33563323, 2021). "This truncating variant was found in the ATM gene, abolishing its kinase activity, and thus probably explaining the strong family history of cancer reported by the patient in question, who carried a classified benign BRCA1 variant." (PMID 34855882, 2021). "Drug-driven synthetic lethality, fueled by the seminal discovery of PARPi-induced selective cytotoxicity in BRCA1- or BRCA2-deficient cancer cells, represents a paradigm for developing therapeutics by exploiting tumor-specific genetic deficiencies." (PMID 34772932, 2021).